CRADD (CARD and death domain containing adaptor protein)
Description:
Adapter protein that associates with PIDD1 and the caspase CASP2 to form the PIDDosome, a complex that activates CASP2 and triggers apoptosis. Also recruits CASP2 to the TNFR-1 signaling complex through its interaction with RIPK1 and TRADD and may play a role in the tumor necrosis factor-mediated signaling pathway.
Synonyms: RAIDD; MRT34
Tractability: PROTAC: ubiquitination databases record sites on it; its protein half-life has been measured.
Gene: Protein-coding gene on chromosome 12 (93,677,375 to 93,894,840, forward strand). Ensembl gene ENSG00000169372.
Subcellular location: Cytoplasm; Nucleus
Subcellular location (Human Protein Atlas): Cytosol; Nucleoplasm
Gene Ontology:
Molecular function: death domain binding; protease binding; protein binding; protein-macromolecule adaptor activity
Biological process: apoptotic signaling pathway; cellular response to mechanical stimulus; positive regulation of apoptotic process; DNA damage response; extrinsic apoptotic signaling pathway via death domain receptors; positive regulation of apoptotic signaling pathway; regulation of apoptotic process; signal transduction
Cellular component: endopeptidase complex; cytoplasm; cytosol; nucleolus; nucleus
Genetic constraint (gnomAD): Loss-of-function variants: 8 observed, 14.44 expected, observed/expected ratio (o/e) 0.55, 90% interval 0.32 to 1. The upper end of that interval is the gene's LOEUF score, 1, which puts it in group 4 of 6, group 1 being the genes least tolerant of losing a copy. Missense variants: 201 observed, 229.47 expected, observed/expected ratio (o/e) 0.88, 90% interval 0.78 to 0.99. Synonymous variants: 103 observed, 98.06 expected, observed/expected ratio (o/e) 1.05, 90% interval 0.89 to 1.24.
Gene-disease validity (ClinGen):
ClinGen rates the evidence that CRADD causes each of these diseases.
syndromic intellectual disability (autosomal recessive): Definitive. A intellectual disability that is part of a larger syndrome.
Homologues: Orthologues: chimpanzee CRADD (99% identical), macaque CRADD (97% identical), rat Cradd (90% identical), mouse Cradd (90% identical), guinea pig CRADD (88% identical), pig CRADD (88% identical), dog CRADD (88% identical), tropical clawed frog cradd.2 (49% identical), zebrafish cradd (47% identical).
Diseases named in the same sentence as CRADD in open-access papers:
CRADD is named in the same sentence as 12 diseases in open-access papers, as found by Europe PMC text mining. Sharing a sentence is not in itself a finding about the gene and the disease. The quoted sentences say what the papers report.
Lissencephaly (4 papers, 2018 to 2022). A spectrum of malformations of cortical development caused by insufficient neuronal migration that subsumes the terms agyria, pachygyria and subcortical band heterotopia. "Mutations in the gene encoding the PIDD-interactor, CRADD, have also been linked to autosomal recessive intellectual disability and lissencephaly." (PMID 35052391, 2021). "Mutations in the CRADD gene have been linked with lissencephaly, a condition in which defective neuronal migration leads to cortical underdevelopment and reduced or absent gyri, resulting in ID and/or other neurodevelopmental disorders." (PMID 33414379, 2021). "Biallelic truncating mutations in CRADD—the protein bridging PIDD1 and caspase-2—have been reported in intellectual disability (ID), and in a form of lissencephaly." (PMID 33414379, 2021).
osteoarthritis (1 paper, 2022). A noninflammatory degenerative joint disease occurring chiefly in older persons, characterized by degeneration of the articular cartilage, hypertrophy of bone at the margins and changes in the synovial membrane. "For seven genes (ALDH1A2, CHMP1A, CRADD, FAM53A, LTBP1, RPP25, and TGFA), we found evidence that GWAS signals for osteoarthritis colocalize with mQTLs in these genes and are additionally associated with gene expression levels in the same tissue." (PMID 35679866, 2022). "We found such an eQTL effect below nominal significance levels for five genes in low-grade osteoarthritis cartilage (ALDH1A2, CHMP1A, FAM53A, RPP25, and TGFA), two genes in high-grade osteoarthritis cartilage (FAM53A and LTBP1), and one gene in synovium (CRADD)." (PMID 35679866, 2022).
Pachygyria (1 paper, 2024). Pachygyria is a malformation of cortical development with abnormally wide gyri with sulci 1,5-3 cm apart and abnormally thick cortex measuring more than 5 mm (radiological definition). "In the past few years, biallelic pathogenic variants in CRADD and PIDD1 have been associated with LIS, anterior-predominant pachygyria, and ID." (PMID 37880421, 2024).
cancer (6 papers, 2015 to 2026). A tumor composed of atypical neoplastic, often pleomorphic cells that invade other tissues. "In summary, we have shown for the first time that PIP increases the sensitivity of BC cells to apoptosis induced by anti-cancer drugs, which is associated with overexpression of specific pro-apoptotic genes (CRADD, DAPK1, FASLG, CD40, and BNIP2)." (PMID 37085653, 2023). "Of note, PIDD1 and CRADD have been reported to activate caspase-2 in various cellular contexts, including DNA damage or centrosome amplification in cancer cells as well as amyloid-induced neuronal toxicity." (PMID 33414379, 2021).
tumor (6 papers, 2015 to 2023). "Recent single-cell transcriptome sequencing studies on HCC have confirmed that different immune cells express different PANoptosis-related genes (CRADD is upregulated in tumor-specific infiltrating regulatory T cells; TNF is upregulated in cytotoxic FGFBP2+ double‐positive T cells)." (PMID 37662906, 2023).
CRADD also shares sentences with these, for which no sentence is quoted: neurodevelopmental disorder (2 papers); autosomal recessive intellectual disability (1); chondrosarcoma (1); Intellectual disability (1); lymphoma (1); neurodegenerative disease (1); Obesity (1).